FECH (ferrochelatase)
Diseases named in the same sentence as FECH in open-access papers (continued):
Sharing a sentence is not in itself a finding about the gene and the disease.
cancer (43 papers, 2011 to 2025). A tumor composed of atypical neoplastic, often pleomorphic cells that invade other tissues. "Low FECH activity of cancer cells causes accumulation of PpIX and other porphyrins in tumors, while normal or high FECH activity results in low accumulation of PpIX in tissues." (PMID 38927525, 2024). "Lower FECH levels have shown a significant association with the cancer grade, the TNM stage, unfavorable prognosis, and impaired immune cell infiltration in clear cell renal cell carcinoma." (PMID 36768924, 2023). "It is rapidly converted to PpIX, which accumulates in the cancer cells deficient in the ferrochelatase enzyme." (PMID 37240309, 2023). "Lower levels of FECH expression were shown to have a strong association with higher grades of cancer and more advanced TNM stages." (PMID 36059798, 2022). "Inhibited FECH caused iron overload in cancer cells and triggered iron concentration, thereby inhibiting cancer cell growth." (PMID 36059798, 2022). "Thirdly, we predicted that a ferrochelatase-deficient cancer cell line, Jurkat, might be similarly susceptible to PPIX induced death." (PMID 37355765, 2023). "Although the detailed mechanism of PpIX accumulation in cancer cells remains unclear, possible causes include reduced ferrochelatase activity through the heme biosynthetic pathway, impaired intracellular negative feedback mechanisms, and/or impairment of its excretion." (PMID 33138188, 2020). "In cancer cells, accumulation of PpIX occurs due to reduced activity of ferrochelatase (FECH) and dysregulation of porphyrin transport systems." (PMID 41404060, 2025). "PpIX accumulates selectively in cancer cells due to the inherently lower activity of PpIX-metabolizing enzyme, ferrochelatase (FECH), than in normal cells." (PMID 41291487, 2025). "The increased PpIX accumulation in cancer cells is often attributed to their lower ferrochelatase (FECH) levels." (PMID 36768924, 2023). "Molecular docking analyses indicated high binding affinities, particularly with FECH, suggesting anti-angiogenic properties and potential applicability in cancer therapy." (PMID 38138609, 2023). "Because of the relationship between PPIX formation and cell death in cancer cells, we interrogated the cancer dependency map (DepMap) for cell lines reliant on the terminal enzyme in heme biosynthesis, FECH." (PMID 37355765, 2023). "As seen in the Warburg effect, the ferrochelatase enzyme becomes inactive in cancer cells, resulting in an accumulation of PpIX." (PMID 37240309, 2023). "PpIX accumulates in cancer cells because of the low activity of ferrochelatase, an enzyme that metabolizes PpIX to heme." (PMID 35742921, 2022). "Owing to the Warburg effect, cancer cells downregulate ferrochelatase, an enzyme that incorporates Fe2+ into PpIX in the final step of heme synthesis, resulting in selective accumulation of PpIX in cancer cells’ mitochondria." (PMID 35842630, 2022). "Inactivation and downregulation of FECH play pivotal roles in selective accumulation of PpIX in cancer cells, while in normal cells FECH is positively regulated at transcriptional and translational levels." (PMID 34575450, 2021). "The heme production is low in cancer cells owing to the reduced activity of ferrochelatase enzyme in the heme cycle, which leads to a build-up of PpIX in the cancer cells." (PMID 34402266, 2021). "Recent studies showed that a novel anti-cancer drug, Alectinib, an orally available, highly selective, potent second-generation inhibitor of anaplastic lymphoma tyrosinkinase binds to ferrochelatase." (PMID 34461853, 2021). "The difference in PpIX accumulation in cancer and normal cells is driven by its active conversion through the heme biosynthetic pathway and ferrochelatase (FECH)." (PMID 34575450, 2021).
cancer (continued). "The increase in the emission intensity at wavelengths greater than 600 nm noticed in this study can be credited to PpIX, which is accumulated in cancer cells owing to the reduced activity of the ferrochelatase enzyme in cancer cells." (PMID 34402266, 2021). "Since the ferrochelatase enzyme is inhibited in cancer cells, there is an increase in PpIX fluorescence from cancer cells." (PMID 34402266, 2021). "As the terminal enzyme in the heme biosynthesis pathway, MEK inhibition suppressed FECH activity to convert Protoporphyrin IX into heme in various human normal and cancer cell lines." (PMID 31295943, 2019). "To date, most studies looking at alterations in cancer and their impact on PpIX synthesis have focussed on the mitochondrial enzymes in the haem biosynthesis pathway, coproporphyrinogen oxidase and ferrochelatase." (PMID 31406300, 2019). "There is evidence of reduced FECH expression in cancer, which would be expected to result in the accumulation of PpIX." (PMID 31406300, 2019). "Since the decreased activity of the enzyme Ferrochelatase has been reported for several types of cancer our future work will focus on comparisons between different cancer cell lines." (PMID 30169536, 2018). "A lower ferrochelatase activity in malignant tumor tissue was proposed to be responsible for an accumulation of PpIX." (PMID 27564260, 2016). "The expression levels of ferrochelatase and frataxin, which transports mitochondrial labile iron ion to ferrochelatase, were also lower in cancer specimens." (PMID 25822972, 2015). "Cells with high rates of metabolic activity, such as cancer cells, inflammatory cells, and bacteria have lower amounts of ferrochelatase (FECH), an enzyme capable of metabolizing PpIX, so the production of photoactive porphyrins is more pronounced than in healthy cells." (PMID 38927525, 2024). "This implies that other cancer cells, such as those harboring impaired FECH function, might also be vulnerable to this form of cell death." (PMID 37355765, 2023). "It should be noteworthy that PpIX selectively accumulates in cancerous cells rather than in healthy cells as it is the precursor for heme via the ferrochelatase reaction, which is the rate-limiting enzyme in the whole pathway with reduced expression and/or activity in the cancer cells." (PMID 37445603, 2023). "To determine whether low FECH expression in cancer is a generalized phenomenon, we began by analyzing the FECH expression pan-cancer and compared it with that in the corresponding adjacent healthy tissues in the TCGA dataset." (PMID 36059798, 2022). "Inspired by this concept, we developed a 5-ALA and CAT co-delivery system based on a theranostic microneedle patch (MN-CCPCA) that forces cancer cell to release the false signal of a “heme deficiency” and thus shuts down the outflow of PpIX through the cascaded downregulation of HIF-1α and FECH." (PMID 36266306, 2022). "Another enzyme with altered activity in cancer cells is ferrochelatase." (PMID 35055109, 2022). "Recent studies showed that a novel anti-cancer drug, Alectinib, is able to bind the FECH-enzyme." (PMID 34461853, 2021). "To date, it has been attributed to the distinctive nature of cancer cells, primarily, to reduced FECH activity and to the limited availability of iron in cancer cells or to the reduced availability of nicotinamide adenine dinucleotide phosphate (NADPH) provision." (PMID 32331454, 2020). "An obvious question is why FECH expression is repressed in some cancers." (PMID 31406300, 2019). "FECH mRNA expression levels in carcinomas strongly negatively correlated with PpIX accumulation." (PMID 30959982, 2019). "Cancer cells show an accumulation of PPIX due to inactivation or downregulation of Ferrochelatase." (PMID 30169536, 2018). "However, it is accepted that reprogrammed cancer cell metabolism induces the saturation of FECH and PpIX accumulation by activating heme biosynthesis, owing to TCA cycle metabolite accumulation." (PMID 28939850, 2017).
cancer (continued). "However, ferrochelatase is inactive in various cancer types, including BC." (PMID 39001362, 2024). "Importantly, the reduction of the activity of FECH may then contribute to an increase in PpIX accumulation inside cells, which has been proven in colorectal and cancer cells." (PMID 35055109, 2022). "Therefore, the suppression of FECH might contribute to the intracellular accumulation of PpIX in carcinomas." (PMID 30959982, 2019). "The inactivation of ferrochelatase and ABCG2 in cancer cells leads, on the one hand, to impaired heme production and the impaired excretion of protoporphirin IX." (PMID 38256035, 2024). "Inhibiting MEK decreased HIF-1α expression and FECH activity and increased 5-ALA-induced PpIX accumulation in cancers." (PMID 36768924, 2023). "Ferrochelatase (FECH) is an enzyme that performs a significant function in the onset and progression of many distinct kinds of malignant tumors." (PMID 36059798, 2022). "For the non-cancer HFFF2 cells, a decrease in the level of all mRNA tested, FECH but also PPOX and ABCG2, was indeed observed following combination of all treatments." (PMID 35886979, 2022). "We previously reported that inhibition of oncogenic Ras/MEK increases PpIX accumulation in cancer cells by reducing PpIX efflux through ATP-binding cassette sub-family B member 1 (ABCB1) and ferrochelatase (FECH)-catalysed PpIX conversion to haem." (PMID 33335181, 2020). "In cancer cells, the lack of the ferrochelatase enzyme leads to an accumulation of PpIX and consequently to an increased production of ROS." (PMID 37240309, 2023). "In carcinomas, the intracellular PpIX concentration showed a strong negative correlation with the relative FECH mRNA levels (r = −0.6368, p = 0.0326)." (PMID 30959982, 2019). "Furthermore, we confirmed that the Ras/MEK-RSK-ABCB1 and Ras/MEK-HIF-1α-FECH axes are involved in the regulation of PpIX accumulation in human cancers, as inhibition of RSK, HIF-1α, or ABCB1 increased PpIX accumulation in multiple human cancer cell lines." (PMID 33335181, 2020).
autosomal dominant disease (2 papers, 2009 to 2018). Autosomal dominant form of disease. "EPP appears to be inherited as an autosomal dominant disease, the clinical expression of which is modulated by the presence of the hypomorphic FECH IVS3-48C allele trans, but recessive inheritance with two mutated FECH alleles has also been described." (PMID 19744342, 2009).
infection (2 papers, 2017 to 2025). The state of being infected such as from the introduction of a foreign agent such as serum, vaccine, antigenic substance or organism. "We expanded human umbilical cord HSCs and differentiated them into erythroblasts for 16 days after infection with a lentiviral vector encoding either a control shRNA or FECH shRNA." (PMID 40663422, 2025).
metabolic disease (2 papers, 2017 to 2024). A congenital disorder (due to inherited enzyme abnormality) or acquired (due to failure of a metabolically important organ) disorder resulting from an abnormal metabolic process. "Partial deficiency in ferrochelatase (FECH) gene expression results in erythropoietic protophyria (EPP), an inherited metabolic disorder." (PMID 28360925, 2017).
FECH also shares sentences with these, for which no sentence is quoted: genetic disorder (7 papers); migraine (3); bile duct obstruction (2); liver failure (2); adenocarcinoma (1); age-related macular degeneration (1); anaplastic astrocytoma (1); atrial septal defect (1); Barrett's oesophagus (1); Clear Cell Renal Cell Carcinoma (1); Congenital erythropoietic porphyria (1); diffuse astrocytoma (1); elliptocytosis (1); hematopoietic diseases (1); hemochromatosis (1); Hemoglobinopathies (1); hepatoma (1); medulloblastoma (1); migraine with aura (1); migraine without aura (1); Obesity (1); ovarian carcinoma (1); parasitic infections (1); Parkinson’s (1); primary immunodeficiency (1); red blood cell disorders (1); renal cell carcinoma (1); retinopathy of prematurity (1); rheumatoid arthritis (1); sarcoma (1).
A further 4 diseases each share a sentence with FECH in 1 paper.